MTOR (mechanistic target of rapamycin kinase)
Diseases named in the same sentence as MTOR in open-access papers (continued):
Sharing a sentence is not in itself a finding about the gene and the disease.
cancer (continued). "mTOR hyperactivation is induced by a hypercaloric diet, proinflammatory cytokines, BCAA and dysregulation associated with various systemic pathologies, including IR, cancer and CVD." (PMID 39200267, 2024). "Pathways in cancer, autophagy, apoptosis, cellular senescence, and MTOR signaling are among them." (PMID 39594641, 2024). "The PI3K/Akt/mTOR pathway axis is one of the most frequently altered pathways in human cancers." (PMID 38542151, 2024). "Moreover, the dysregulated activity of mTOR is involved in many pathophysiological conditions, such as aging, Alzheimer's disease, diabetes, obesity, and cancer formation 13-15." (PMID 38817860, 2024). "According to pre-clinical studies, the clinical translation of miRNAs could target mTOR as therapeutic agents to improve RT outcomes holds promise for enhancing the efficacy of cancer treatment." (PMID 38965615, 2024). "Common oncogenes and tumor suppressor genes involved in the mitogen-activated protein kinase (MAPK), phosphoinositide 3-kinase (PI3K), and mammalian target of rapamycin (mTOR) pathways have been heavily reported in most cancer types and can affect mitochondrial function." (PMID 38255314, 2024). "In addition, several genes of the parallel PI3K/AKT pathway were more frequently mutated in CDX2-suppressed cancers, with the differences for PTEN, MTOR, and RICTOR reaching significance." (PMID 39452477, 2024). "For instance, combining natural compounds with PI3K/Akt/mTOR inhibitors may mitigate toxicity, representing a significant approach to targeted cancer therapy (Yu, Wei, and Liu 2022)." (PMID 39723045, 2024). "The mTOR signaling pathway is frequently dysregulated in cancer and metabolic diseases." (PMID 39247820, 2024). "By regulating the LAMP2a/RNH1/miR‐99a/mTOR signaling axis to make anti‐cancer effects, aripiprazole administration may be an efficient strategy for CRC therapy." (PMID 39513392, 2024). "The regulation of cell proliferation, differentiation, survival, apoptosis, invasion, migration, angiogenesis, and metastatic spread of cancer cells is connected with various signaling pathways, including mTOR, PI3K, protein kinase B (Akt), MAPK/ERK, Wnt, Notch, and Hedgehog." (PMID 39104398, 2024). "Thus, mTOR activity levels must be titrated in cancer cells such that the cell can meet the high energy demands of cell growth/proliferation without causing cell death." (PMID 38915098, 2024). "The expression levels of total and phosphorylated proteins were then assessed, revealing a significant reduction in phosphorylated AKT and mTOR in sh-DNMT1 cancer cells, although the overall protein expression levels of PI3K and AKT did not exhibit substantial alterations." (PMID 38755637, 2024). "The available data suggest that mTOR inhibition and subsequent eIF2α phosphorylation as the key molecular axis ensuring stem cell proteostasis can promote stem-cell-like phenotypes in dormant cancer cells." (PMID 38418814, 2024). "Moreover, the PI3K/AKT/mTOR signaling pathway is frequently activated and involved in proliferation, survival, invasion and metastasis in various human cancers." (PMID 38817869, 2024). "The mTOR signaling pathway is involved in many cancers, and paclitaxel may have dual effects on this pathway." (PMID 39584140, 2024). "Although the ACSM recommends resistance exercise for patients with cancer, research indicates that the Akt/mTOR signaling pathway, essential for muscle growth, is unaffected or hyperactivated in cancerous conditions, differing from its regulation in healthy states." (PMID 39727676, 2024).
cancer (continued). "Therefore, inhibitors targeting the PI3K/Akt/mTOR pathway and, consequently, cap-dependent translation have evolved as therapeutic strategies for cancer treatment." (PMID 38476632, 2024). "According to reports, cancers with abnormal mTOR activation account for > 70% of all cases." (PMID 38225540, 2024). "Given that LMs often are caused by some of the same mutations in the PI3K/AKT/mTOR and RAS/MAPK pathways that promote cancer, several drugs already approved for cancer treatment can be repurposed for patients with LM, thus shortening the clinical approval process." (PMID 38488007, 2024). "Additionally, we investigated the relationship between mTOR activation and cancer stem cell (CSC) characteristics, given that CSC is thought to be a driving factor for chemoresistance and cancer relapse." (PMID 38560690, 2024). "Additionally, we illustrated that mTOR inhibitors enhance the cytotoxic effect of cisplatin, by employing cancer stem cell characteristics." (PMID 38560690, 2024). "The PI3K/mTOR pathway is important for metabolism, growth, and mRNA translation, and is often over-activated in many cancer cells, we can inhibit this signaling pathway to prevent cancer cell growth." (PMID 38238825, 2024). "In addition, TVB3664, when combined with cabozantinib, has potential in downregulating multiple cancer-associated pathways, including AKT/mTOR, and in inhibiting cell proliferation." (PMID 39489738, 2024). "In addition, Beclin-1 regulates autophagy in human cancers by interacting with ATGs, mTOR, and AMPK." (PMID 39650649, 2024). "Recent studies have suggested that YME1L could be important for Akt-mTOR activation in cancer cells." (PMID 38769124, 2024). "The PI3K/Akt/mTOR signaling is essential for the regulation of many basic cellular processes including protein synthesis and the dysregulation of PI3K/Akt/mTOR signaling is associated with cancer progression." (PMID 39242581, 2024). "Treatment with metformin led to increased overall and disease-free survival in CRC diabetic patients, opposing cell cycle and growth, cancer stem cells and metastatic ability via mammalian target of rapamycin (mTOR) and PI3K/Akt pathway inhibition and AMPK activation." (PMID 38667278, 2024). "Furthermore, enhanced expression of cyclic-dependent kinase 2 (CDK2) induces the malignant transition of cancer cells through AKT/mTOR signal." (PMID 39349424, 2024). "Analysis of the Cancer Dependency Map (DepMap) classified PIK3CA to be a strongly selective dependency in other cancer types, however, MTOR was identified to be a common dependency in both healthy and cancerous cells, providing further justification for targeting PI3K in DIPG." (PMID 38319732, 2024). "In addition, available data suggests that metformin has some effects against cancer by inhibiting mTOR and cancer cell proliferation." (PMID 38333748, 2024). "Inhibitors of this PI3K/AKT/mTOR pathway were approved for cancer treatment." (PMID 38473300, 2024). "In addition, these findings revealed a connection between miRNAs − 410 and the PTEN/Akt/mTOR axis in cancers." (PMID 38965615, 2024). "First, DNA/RNA-targeting anti-cancer drugs have been co-treated with mTOR pathway inhibitors." (PMID 39349424, 2024). "Moreover, 18F-FDG PET serves as a diagnostic tool to assess the effectiveness of cancer cell treatment through fibroblast growth factor receptors (FGFR)-targeted therapy, which is activated by FGFR and mTOR/HK2 axis." (PMID 38974238, 2024). "Paradoxically, mTOR inhibition might favor the emergence of cancer cells that are resistant to chemotherapy." (PMID 39339243, 2024). "In vitro studies on LCSC6 revealed widespread inhibition of the mTOR pathway, in parallel with a massive accumulation of bioactive dihydroceramide lipids, indicating that NanoFEN was able to activate the multifactorial program in cancer cells." (PMID 38794242, 2024).
cancer (continued). "Over the years, targeting malfunctioning PI3K/AKT/mTOR has been considered an attractive therapeutic target, especially in the MBC metastatic setting, as activation of this signalling axis has been linked to cancer progression and metastasization." (PMID 39322687, 2024). "Indeed, targeting the mTOR pathway has shown promise in cancer treatment in both research and clinical settings 19-21." (PMID 39668819, 2024). "In addition, a significant reduction in Akt and mTOR phosphorylation involved in the PI3K/Akt/mTOR signalling pathway, which is critical for cancer, was observed." (PMID 39685620, 2024). "Phase I studies demonstrated that inhibiting the IGF-1R compensatory responses with mTOR inhibition could yield favorable clinical activity in advanced cancers, particularly in estrogen receptor (ER)-positive/high-proliferative breast carcinoma." (PMID 38584599, 2024). "Since the mTOR signaling pathway is reported to regulate VEGFA expression and promote ccRCC angiogenesis and progression, we tested whether the mTOR signaling pathway is one of the key pathways mediating the cancer-related function of RNF26." (PMID 38890443, 2024). "Secondly, diverse downstream pathways like EGFR/MAPK, AKT/mTOR and WNT/β-catenin were involved in different cancer types, which might cause different pathological behaviors 73,99,175." (PMID 38385078, 2024). "Ultimately, our findings may provide a novel strategy for patients with HPV− HNSCC by cotargeting mTOR and key cell cycle–regulating molecules, which can also have an impact in multiple cancer types that fail to respond to CDK4/6 inhibitors as single agents." (PMID 38954773, 2024). "Targeting this pathway could be relevant in cancer treatment, as studies in murine models have shown that the mTOR inhibitor everolimus reduced cancer mortality and polyp formation." (PMID 39766864, 2024). "Consequently, the clinical potential and importance of mTOR in effective cancer therapy are increasing." (PMID 39349424, 2024). "The PI3K/Akt/mTOR pathway is crucial for cell proliferation, apoptosis, autophagy, metabolism, and cell cycle progression, representing a key survival pathway often dysregulated in various human cancers." (PMID 38628670, 2024). "We successfully delivered the PI3K/mTOR inhibitor into cancer cells." (PMID 40115434, 2024). "This presents mTOR as a critical target for anti-cancer strategies." (PMID 38891847, 2024). "Currently, there are extensive studies and applications of increasing numbers of drugs besides immune checkpoint inhibitors, including mTOR (mammalian target of rapamycin) inhibitors, which may potentially treat malignant tumors." (PMID 38804848, 2024). "In addition to its effects on mTOR suppression, 1,25-D negatively regulates energy metabolism in cancer cells, including glucose and lipid metabolism, protection from oxidative stress, and cancer progression." (PMID 38846332, 2024). "The PI3K/AKT/mTOR signaling pathway plays a vital role in regulating key cellular processes such as growth, proliferation, and survival, and is often dysregulated in various cancers, including OSCC." (PMID 39458918, 2024). "TBK1 promotes cancer cell survival and proliferation by phosphorylating mTOR at Ser 2159." (PMID 39061024, 2024). "Likewise, the PI3K/Akt/mTOR activation has been revealed to regulate cancer cell growth and survival in different human cancers." (PMID 38965615, 2024). "Therefore, the mTOR pathway inhibition observed in both quiescent stem cells and quiescent cancer cells appears to be a molecular event indispensable for cell dormancy." (PMID 38418814, 2024). "One of the well-known oncogenic alterations of the mTOR pathway is the RICTOR amplification, which has been shown to contribute to progression and metastasis in certain cancers through its association with the molecular signaling behind these processes (e.g., Wnt/β-katenin, MAPK/ERK pathways)." (PMID 38339294, 2024).
cancer (continued). "For instance, Trichostatin A, a drug that influences miR-204 expression, can increase the expression of ERα and, alongside Tamoxifen (TAM), enhance cancer cell sensitivity to treatment by reducing the activity of pathways such as AKT/mTOR, which are involved in cancer cell survival." (PMID 39199587, 2024). "Here, we show that cancer cells, through the secretion of EV, push surrounding cells (malignant and non‐malignant) towards increased glycolysis via phosphorylation of AMPKα and mTOR." (PMID 39001708, 2024). "Aberrant Akt/mTOR activation is involved in multistep tumorigenesis in a variety of cancers, thereby suggesting that the inhibition of mTOR may have therapeutic potential." (PMID 38474373, 2024). "In addition, it has been shown that inhibiting the PI3K/AKT/mTOR pathway induces cellular senescence in various cancers." (PMID 39850601, 2024). "Similarly, Rehman and colleagues induced a reversible state of dormancy in cancer cells, from which tumor cells emerged 14 days after withdrawal of the mTOR inhibitor INK128." (PMID 38418814, 2024). "Targeting mTOR has emerged as an effective therapeutic approach for various cancers, including CRC." (PMID 38671459, 2024). "Combining PD-1 blockade with mTOR pathway targeting could potentially enhance the antitumor efficacy against cancer." (PMID 39070142, 2024). "These suggest that the effects of TAC on mTOR activation may vary depending on the cell type and that TAC could positively influence tumorigenic mTOR activation in certain cancer or pre-cancer cells." (PMID 38341510, 2024). "Transcriptomic analysis revealed significant increases in cancer hallmark pathways, such as epithelial to mesenchymal transition (EMT), PI3K/AKT/mTOR and transforming growth factor (TGF)β pathway signature scores, in cell lines unresponsive to combination treatments." (PMID 39103541, 2024). "The role of mTOR inhibitors (mTORi) in cancer and their safety in TSC have been established." (PMID 38846332, 2024). "Pyruvate dehydrogenase phosphatase 1 (PDP1) could accelerate intracellular ATP production and promote cancer progression through mTOR activation." (PMID 38506093, 2024). "The Akt/mTOR pathway has been widely studied in tumorigenesis and is generally activated in cancer." (PMID 38668684, 2024). "Mitochondrial hyperfunction can foster Akt-mTOR activation in cancer cells." (PMID 38228583, 2024). "Because of its diverse role in regulating essential cellular functions, alterations in mTOR signaling can lead to the development of a wide range of diseases, including metabolic, cardiovascular, or neurodegenerative disorders, accelerated aging, and cancer." (PMID 38339294, 2024). "However, the limitation of this study is that it did not evaluate the direct association of the apoptosis-mitochondrial dependent pathway or the regulation of the PI3K/Akt/mTOR pathway in apoptosis following CGEtOAc and sorafenib treatment in cancer cells." (PMID 38527038, 2024). "Blocking PD-L1 by antibody reduces mTOR activity and glycolytic metabolism in cancer cells." (PMID 38726017, 2024). "In previous studies, the PI3K/AKT pathway was shown to be a classical oncogenic signaling pathway that is involved in the occurrence, development and chemotherapy resistance of various tumors, and downregulated expression of NEAT1 inhibited the PI3K/AKT/mTOR signaling pathway in many cancer cells." (PMID 38898019, 2024). "SIRT1 interacts with mTOR to regulate autophagy in human cancers." (PMID 39403142, 2024). "When the TSC1 gene is mutated or its function is impaired, it may lead to excessive activation of the mTOR signaling pathway, promoting cancer cell proliferation, metastasis, and tumor development." (PMID 38890443, 2024). "Furthermore, AMPK negatively regulates the mTOR signalling pathway, inhibiting cancer proliferation and growth." (PMID 38575697, 2024). "mTOR signaling and cellular metabolism are mutual determinants in cancer." (PMID 37848634, 2024).
cancer (continued). "Moreover, because quercetin reduces β-catenin and HIF-1α stabilization, activates caspase-3, and inhibits Akt, mTOR, and ERK phosphorylation, it promotes cell viability loss, apoptosis, and autophagy in cancer." (PMID 39273552, 2024). "Thus far, the role of the mTOR pathway in the macrophage-mediated phagocytosis of cancer cells remains inadequately defined." (PMID 39766137, 2024). "Additionally, some reports have indicated that leukotrienes affect the PI3K/AKT/mTOR cascade when exerting their biological activity, suggesting that multiple pathways are involved in the regulation of cancer cell proliferation." (PMID 39064957, 2024). "Thus, mTOR activity levels appears to be carefully regulated in cancer cells such that the cell can maintain the high energy demands of cell growth/proliferation without causing cell death." (PMID 38915098, 2024). "Cancer cells can upregulate mTOR pathway activity, even in the presence of PI3K inhibitors." (PMID 38172946, 2024). "The mTOR pathway plays an important role in the regulation of cell metabolism, survival, growth, and protein synthesis in both normal physiological and pathological conditions, especially in cancer." (PMID 38967692, 2024). "Furthermore, the PI3K/AKT/mTOR signaling pathway is a fundamental pathway in cancer development, and its abnormal activation significantly contributes to the chemoresistance exhibited by tumor cells." (PMID 38345573, 2024). "H19 also promotes autophagy in cancer cells via the PI3K–Akt–mTOR pathway." (PMID 38355574, 2024). "These small, non-coding RNAs contribute to the intricate molecular landscape of tumors by modulating the expression of oncogenes and tumor suppressors, including those involved in the PI3K/AKT/mTOR pathway, thereby adding another layer of complexity to cancer biology." (PMID 39850811, 2024). "In comparison with the HDAC inhibitor treatment, VEGF, Vimentin, p-PI3k, p-Akt, and p-mTOR protein expression levels were significantly decreased in the cancer cells treated by HDAC inhibitor+PI3K inhibitor; while E-cadherin protein level was significantly increased (P<0.05)." (PMID 38645502, 2024). "This suggests that TRIM26 may play a regulatory role in the transduction cascade of mTOR signaling, which is commonly disrupted in human cancer." (PMID 38773612, 2024). "Importantly, we identified SF3B3 as a critical regulator of mTOR splicing and autophagy in multiple cancers." (PMID 38671459, 2024). "Furthermore, SREBP1 has been found to interact with other oncogenic signaling pathways, such as the PI3K/Akt/mTOR pathway, to promote cancer cell growth and survival." (PMID 38553715, 2024). "Importantly, there were significant inverse correlations between miR-181c/d expression and cancer-related oncogenic pathways as mTOR and Hedgehog." (PMID 38598008, 2024). "The PI3K/AKT/mTOR signaling pathway is crucial in regulating cell growth and cancer growth." (PMID 39830658, 2024). "Additionally, Notch signaling interacts with other key pathways, such as PI3K/AKT, mTOR, and β-catenin, further contributing to cancer progression." (PMID 39682234, 2024). "Consequently, targeting the PI3K/AKT/mTOR signaling pathway represents a promising therapeutic approach for combating cancer, including HNC, paving the way for the development of effective antineoplastic agents." (PMID 39469621, 2024). "EGFR activation triggers two key signaling cascades in cancer: the PI3K/AKT/mTOR and MAPK pathways." (PMID 39126121, 2024). "The PI3K/Akt/mTOR pathway is crucial for regulating cellular processes such as growth, proliferation, survival, and metabolism, and its dysregulation is frequently observed in various cancers." (PMID 38994962, 2024). "PI3K/AKT/mTOR pathway: The PI3K/AKT/mTOR signaling axis is integral to cell growth, metabolism, and survival, and its dysregulation through aberrant DNA methylation patterns is a hallmark of various cancers, including CRC." (PMID 39370455, 2024).